CXCR3 (C-X-C motif chemokine receptor 3)
Diseases named in the same sentence as CXCR3 in open-access papers (continued):
Sharing a sentence is not in itself a finding about the gene and the disease.
tumor (continued). "We found that the PBNK cells express prime chemokine receptors, such as CXCR3, CXCR4, CCR5, and CXCR6, that match chemokines produced by the studied tumor cells." (PMID 33919155, 2021). "Sitagliptin increased overall CXCR3-mediated CD8+ T-cell trafficking to the tumour and enhanced the activation and proliferation of CD8+ T-cells in tumour tissue and the peritoneal cavity." (PMID 33513866, 2021). "Chemokines such as CXCL8, CXCR3, CXCL1, and CXCL5 regulate the tumor immune response in tumor microenvironment." (PMID 33955820, 2021). "Phenotypically, the spleen and tumor-derived donors expressed similar levels of Bcl-2, TIM3, CXCR3, PD-1, and had undergone similar patterns for memory vs effector differentiation as determined by CD62L, CD127, and KLRG-1." (PMID 34867942, 2021). "In turn, the irradiated tumor cells significantly enhanced migration of CCR5+ CD8+ and CXCR3+CD8+ T cells to the TME." (PMID 33469123, 2021). "Overexpression of CXCL10 has been shown to promote tumor growth, migration, and invasion via targeting of the cognate receptor chemokine (CXC-motif) receptor (CXCR3)." (PMID 33681290, 2021). "It is therefore likely that the increased expression of CXCR3 seen on the T cells in draining lymph node in vivo is in response to paracrine CXCL9 and CXCL10 signals possibly from the tumor." (PMID 34336705, 2021). "For example, CXCR3 and its ligand CXCL9 were critical for a productive CD8+ T cell response in tumor-bearing mice treated with anti-PD-1, indicating that the CXCR3 chemokine system was an indicator of the clinical sensitivity to anti-PD-1 mAb." (PMID 34692696, 2021). "This further attracts CXCR3-expressing Th1 cells, CD8+ T cells, and NK cells into tumor tissues by a positive feedback mechanism." (PMID 34885241, 2021). "Vaccination enhanced the expression of CCR5+ IFN-γ+ and CXCR3+IFN-γ+ on CD8+ T cells, which led to a significant increase in CCL5 and CXCL9/10 secretion from irradiated tumor cells." (PMID 33469123, 2021). "TGF-β has been well accepted as an immunosuppressive cytokine in cancer progression, which can suppress the expression of chemokine receptor CXC motif 3 (CXCR3) in CD8 + T cells and thus limit the tumor trafficking." (PMID 34422810, 2021). "In patient-derived RCC samples, increased expression of CXCR3 and CC chemokine receptor 5 (CCR5) on tumor-infiltrating T lymphocytes was found." (PMID 34503058, 2021). "In contrast, analysis of immune-fibroblast interactions highlighted CXCL12 expression by fibroblasts, with the potential to recruit CXCR3/4-expressing CD8 T cells and MNPs that was reduced in tumor." (PMID 34936871, 2021). "Two of the key factors that are required for tumour infiltration of NK cells are IFN-γ and the chemokine receptor CXCR3." (PMID 34090499, 2021). "For example, chemokines (CXCL9 and CXCR3) can exert antitumor responses by recruiting CD4+ T cells, CD8+ T cells, NK cells and M1 macrophages into the tumor center." (PMID 34335575, 2021). "IFN-γ also promotes the recruitment of cytotoxic CD27high NK cells in a CXCR3-dependent manner through upregulating the production of CXCL9 and CXCL10 by tumor cells." (PMID 35008589, 2021). "Based on insights from mechanistic studies that showed chemokine receptors CXCR3, CCR2, and CCR5 are critical for T cell trafficking to the tumor site, several preclinical studies have investigated strategies that increased chemokine signaling in CAR-Ts." (PMID 32244520, 2020). "Many strategies such as expressing chemokine receptors CXCR2/CCR2b, CXCR3 and use of oncolytic virus to secrete chemokines RANTES, IL-15 to drive CART cells to tumor sites are being actively tested to drive CART cells to tumor sites in non-GBM tumors." (PMID 33281826, 2020). "IL-17A, predominantly secreted from Th17 cells, inhibited STAT3-dependent CXCR3 expression on CD8+ T cells, leading to decreased CD8+ T cell migration to tumor tissues." (PMID 32503584, 2020).
tumor (continued). "Current prognostic markers include chemokines receptors CXCR3, CXCR4 and CXCR7, which are known to be involved in multiple tumour progression and metastasis." (PMID 32512633, 2020). "Consistently, “good” bacteria introduction was reported to significantly increase IFN-γ production in spleen and tumor-draining lymph nodes (TDLN) and induce DCs to secrete IL-12, resulting in increased recruitment of CCR9+CXCR3+CD4+ T cells into tumor beds." (PMID 33194652, 2020). "Chemokine receptors such as CXCR3, CXCR4 and CXCR7 play vital roles in the process of tumour progression and metastasis." (PMID 32512633, 2020). "Supernatants derived from tumor tissues markedly facilitated CD8+ T cell migration, which was attenuated by anti-CXCL10 or anti-CXCR3 neutralizing antibodies." (PMID 32503584, 2020). "At this time point, CXCR3 expression in CD8+ TEM and TEMRA cells was appreciably decreased, suggesting that CXCR3high cells had migrated into the tumour injection site." (PMID 32439888, 2020). "Their migration to inflamed tissues including tumor sites involves a series of chemokine receptors such as CCL3-5/CCR5, CXCL10/CXCR3, and CX3CL1/CX3CR1." (PMID 31991604, 2020). "CXCR3 blockade abolished intratumoral CD8+ T cell infiltration and anti-tumor efficacy of the PD-1 blockade therapy." (PMID 33584713, 2020). "We also probed for myeloid cells expressing CXCR3 (the receptor for CXCL9-11) and CCR2 (one of the receptors for CCL11 and uniquely a receptor for MCP1) within our tumor digests." (PMID 31940491, 2020). "CXCR3 and CXCR5 (e.g., CXCL10-CXCR3, CXCL11-CXCR3, and CXCL13-CXCR5), which belong to the CXC chemokine receptor family, were found highly expressed in tumor T cells." (PMID 32549766, 2020). "To address the mechanisms underlying the antitumor effects of celecoxib, we focused on the tumor microenvironment and examined the levels of chemokines CCL2 and CXCL10 and their receptors, CCR2 and CXCR3, respectively." (PMID 32943658, 2020). "Memory-like T cells within the tumor expressed CD127, CXCR3 and had the potential to proliferate significantly when they were transferred into tumor-bearing mice." (PMID 32845913, 2020). "Previous studies determined the upregulation of genes related to immune cell activation (e.g., CD3D, CD8, CXCR3, CCL5, CXCL9, and CXCL10) in cancer patients with a better prognosis, thereby highlighting the impacts of immune-related genes on tumor progression." (PMID 32775427, 2020). "Furthermore, treatment of tumor bearing animals with myeloid targeting agents enhanced CXCR3-mediated tumor homing resulting in improved survival, highlighting the critical role of CXCR3 mediated T cell chemotaxis as a common pathway to effective anti-tumor immunity." (PMID 32273499, 2020). "In the tumor microenvironment, cDC1s are the main source of CXCL9 and CXCL10 chemokines, which are chemoattractants for CXCR3+ effector cells, such as T cells, NK cells and innate lymphoid cells (ILC1)." (PMID 32075343, 2020). "CXCR3 is a chemotactic receptor on activated T cells, which binds CXCL10 released by tumor cells and by intratumoral activated DCs, following autocrine and paracrine stimulation by type-1 IFNs." (PMID 33281620, 2020). "Reduction in CXCR3+ CD8+ T cells also trended with longer OS (p = 0.02), and tumor shrinkage (p = 0.03)." (PMID 32046729, 2020). "Objective response rate (complete or partial response) was significantly correlated to tumor microenvironment-related SNPs concerning CCL2, NOS3, IL1RN, IL12B, CXCR3, and IL6R genes." (PMID 32733486, 2020). "MAIT cells in circulation have been shown to express receptors for IP-10 (CXCR3) and CCL22 (CCR4), respectively, rendering them receptive to these chemokines, however, what this means for anti-tumor immunity is currently unclear." (PMID 31354725, 2019). "One such chemokine is CXCL11, which specifically attracts CXCR3+ CD8+ cells and undergoes proteolytic alterations induced by the tumor, resulting in failure to attract TILs." (PMID 30828330, 2019).
tumor (continued). "CXCR3, the receptor of chemokine CXCL9, is frequently upregulated in HCC and correlates with tumor size, tumor differentiation, portal invasion, and metastasis." (PMID 31623313, 2019). "Ablation of CXCR3 in blood cells also reduced the levels of IL-10 and TGF-β in tumors, both of which have been shown to inhibit CRC development by dampening tumor-promoting inflammation." (PMID 31775909, 2019). "Considering the expression of CXCR3 variants was not analyzed in these studies, one can only speculate that the inhibitory effect of these chemokines on tumor angiogenesis is driven through CXCR3-B present on endothelial cells, a phenomenon which may be cancer-type-dependent." (PMID 31216755, 2019). "We have identified NFATc3-dependent genes that are known to be involved in tumour migration: COX-2 and CXCR-3." (PMID 31249342, 2019). "CXCR3-targeted AMG487 remarkably decreased metastasis and enhanced host anti-tumor immunity in a 4T1 mammary tumor model." (PMID 31695804, 2019). "HSD fed animals further displayed a higher percentage of CXCR3+ CD4+ T cells in mLN cells, indicative of an increase in TH1 cells in HSD fed tumor-bearing animals." (PMID 31214164, 2019). "To understand if NFATc3 is a critical factor for cytokines and chemokines known to be involved in tumour growth, we evaluated the impact of nuclear NFATc3 on TNF-α, CXCR-3, GM-CSF, IL-2 and CCL-2 mRNA expression." (PMID 31249342, 2019). "In tumor tissue, CXCR3 has been found to be expressed in the cancer cells, peritumoral stromal cells, vascellum, and recruited leucocytes, which could regulate tumor growth, migration, invasion, angiogenesis, and immunity, thus directly or indirectly participating in tumor progression." (PMID 31240220, 2019). "The chemokine receptors CCR1, CXCR3, CCR4 and CCR5 were found to be heterogeneously expressed in ALCL tumor cells." (PMID 31581676, 2019). "CXCL9 and CXCL10, agonists of the CXCR3, promote the recruitment of CD4+ Th1 lymphocytes, NK cells, and CD8+ cytotoxic T lymphocytes (CTL) to the TME, where they exert a potent anti-tumor activity." (PMID 30319638, 2018). "In tumor initiation, circulating Vγ9Vδ2 T cells, activated by the over-produced IPP in cancer cells, express the inflammatory homing chemokine receptors (e.g., CXCR3 and CCR5), guiding them into tumor sites." (PMID 29997627, 2018). "On one hand, they promote immune cell recruitment necessary for tumor control (e.g., CXCL9/10/11 and CXCR3)." (PMID 30420855, 2018). "Successful infiltration depends upon the interaction of adhesion receptors on T cell and tumor endothelium in addition to the match of chemokine receptor of CAR T cells (mainly CCR5, CXCR3) and chemokines secreted by the tumor." (PMID 30613448, 2018). "Accordingly, we identified CXCR3+KLRG1− T cells in tumor-draining lymph nodes, that were capable of seeding tumor-specific Trm responses in the skin following i.v. adoptive transfer." (PMID 30555481, 2018). "IP-10/CXCL10 can recruit CXCR3+ T cells, including CD8+ T cells, which are important for the control of tumor growth, via the CXCR3 receptor expressed on activated T cells." (PMID 30228241, 2018). "CXCR3 and CXCL10 immunoreactivity was mainly localized in epithelial cells within the tumor, but some minor staining was also observed in the inflammatory infiltrate." (PMID 29416784, 2018). "They significantly induced accumulation of tumor specific CD8 T cell in tumor site and increased expression of CXCR3 on tumor infiltration CD8 T cell (p<0.05)." (PMID 30400835, 2018). "It has been demonstrated in various cancers that the tumour microenvironment expresses CXCL10 (IP-10), which leads to Th1-specific recruitment to the site mediated by the CXCL10 receptor CXCR3 expressed on Th1 cells." (PMID 30075815, 2018). "Often the tumor produces insufficient quantities of CCR5, CXCR3 which results in ineffective targeting of tumor sites by CAR T cells." (PMID 30613448, 2018).
tumor (continued). "Our recent publication that targeting mouse CXCR3, the CXCR3A form, decreased tumor metastasis is consistent with these reports." (PMID 27223426, 2017). "In the invasive part of the tumor, LRP1 expression was completely shut down while CXCR3 was still present in tumor cells." (PMID 29146996, 2017). "Gene expression analysis revealed that BCG injection elicits the expression of a vast array of chemokines in tumor lesions, including strong expression of CXCL9, 10, and 11, a set of chemokines that attract T cells expressing the CXCR3 chemokine receptor." (PMID 28424760, 2017). "The results of a recently published study showed that CXCR3 was expressed on significantly fewer CD4+ and CD8+ T lymphocytes in tumor tissue compared to the unaffected tissue." (PMID 29020986, 2017). "While CXCR3 is expressed in both, angiogenic and invasive areas, LRP1 expression is strongly reduced in invasive zones of the tumor." (PMID 29146996, 2017). "TI-Treg cells express a variety of chemokine receptors, including CCR4, CCR5, CCR6, CCR7, CCR10, CXCR3, and CXCR4, and migrate efficiently in response to tumor-derived chemokines." (PMID 29463952, 2017). "In conclusion, this study is the first to demonstrate that TNF‐α, a key mediator in the inflammatory tumour microenvironment, strongly up‐regulated CXCR2 and CXCR3 to enhance migration, invasion, EMT and sphere formation of RCC cells." (PMID 27297979, 2016). "CXCL11, also called I-TAC, a ligand for receptors CXCR3 and CXCR7, attracts CD8+ T cells and NK cells to the tumor or other inflamed sites." (PMID 26956047, 2016). "CXCL10, ligand for CXCR3, is also secreted by CRC cells, which recruits CXCR3+ helper T lymphocytes type 1 (Th1) at the invasion front of CRC and contributes to anti-tumor immunity." (PMID 27136535, 2016). "CXCR3, a G-protein coupled receptor of chemokine CXCL9, is significant in tumor progression and angiogenesis, and also has been found to be correlated with poor prognosis for breast tumors, melanoma, and colon and renal cancer patients." (PMID 26883105, 2016). "CD27high NK cells in mice are orthologs of human CD56bright cells, and in both species, these NK subsets express CXCR3 and are attracted to CXCL9 and CXCL10 chemokines at tumor sites." (PMID 25972872, 2015). "On the contrary, chemokine ligands of CXCR3, CXCR6 and CX3CR1 attract NK cells and T lymphocytes that can elicit anti-tumor responses." (PMID 26062132, 2015). "CXCR3 targeting with the small molecular inhibitor AMG487 significantly reduced metastasis and improved host anti-tumor immunity." (PMID 26485767, 2015). "Consistently, targeting CXCR3 using a small molecular inhibitor (AMG487) significantly suppressed metastasis and improved host anti-tumor immunity." (PMID 26485767, 2015). "Treating tumor-bearing mice with a CXCR3 inhibitor (AMG487) that targets both tumor and host compartments decreased tumor metastasis and simultaneously improved host immune responses." (PMID 26485767, 2015). "Interferon (IFN)-γ-inducible protein (IP)-10 (IP-10) is a potent inhibitor of angiogenesis and can recruit CXCR3+ T cells, including CD8+ T cells, which are important for the control of tumor growth." (PMID 24816916, 2014). "GBM expression of CXCR3 was confirmed in human and murine GBM cell lines and its activation promotes proliferation in vitro and experimental tumor progression in vivo." (PMID 24904289, 2014). "NK cells migrate to lymph nodes mainly by utilizing CXCR3, while their migration to the inflamed tissues including tumor sites involves CCR1, CCR2, CCR5, CXCR3, and CX3CR1." (PMID 24966464, 2014). "NLGP significantly improved the expression level of chemokine receptor CXCR3 and CCR5 and their corresponding ligands that are frequently altered at tumor vicinity, thereby, stimulating proper homing of lymphocytes at tumor site." (PMID 23785504, 2013).
tumor (continued). "Furthermore tumor-expressed CXCL9 was shown to be crucial for immune control of murine cutaneous fibrosarcomas while CXCL11 secretion by genetically modified mouse T cell lymphoma cells (EL4) led to increased infiltration of CD8+CXCR3+ T cells and subsequent tumor rejection." (PMID 23874342, 2013). "Consistent with this notion, we observed significant expansion of CXCR3+ T cells within TDLN and TIL on day 21 of NLGP-treated tumor bearer." (PMID 23326300, 2013). "An expansion of CXCR3+ and CCR5+ T cells was observed in the TDLN and tumor, along with their corresponding ligands." (PMID 23326300, 2013). "RNA and protein levels of two known ligands of CXCR3, CXCL10/IP10 and CXCL11/IP9 were down-regulated in the tumor lines." (PMID 22236567, 2012). "In our earlier study, we have shown that migration of CTL derived from a CRC patient towards autologous tumor cells was mediated by CXCR3 expressed by the T cells, and CXCL11 chemokine secreted by the autologous tumor cells." (PMID 21450101, 2011). "We used immunohistochemistry to identify cells expressing CXCR1, CXCR2, CXCR3, CXCR4, CXCR5 and CCR1 in the tumour islets and stroma in 20 patients with surgically resected NSCLC." (PMID 20429924, 2010). "There was increased expression of CXCR2, CXCR3, and CCR1 in the tumour islets of ES compared with poor survival (PS) patients (p = 0.007, 0.01, and 0.002, respectively)." (PMID 20429924, 2010). "There was significantly increased expression of CXCR2, CXCR3, and CCR1 in the tumour islets of ES compared with PS patients [median 6.5 versus 2.6, (p = 0.007), 12.7 versus 3.2, (p = 0.01), and 24.3 versus 2.4 cells/mm2, (p = 0.002), respectively]." (PMID 20429924, 2010). "Indeed, analysis of OS tumor databases reveals that high intra-tumoral expression of CXCL10 and/or CXCR3 correlates with improved prognosis, consistent with a robust local anti-tumor immune response." (PMID 41516196, 2025). "Similarly, CXCR3 and CXCR4 play pivotal roles in regulating the migration of immune cells to the tumor microenvironment, a process that not only supports immune evasion but also aids in tumor metastasis to distant organs." (PMID 41024311, 2025). "Furthermore, activated CXCR3+ Tregs were found in various tumours and shown to co‐localise with CXCL9+‐cDC1s in the TME of mouse transplantable tumours." (PMID 40878038, 2025). "In conclusion, our findings reveal a novel miR-762/CXCR3 axis that regulates the immunosuppressive microenvironment in OSCC and may be a potential RNA-targeted therapeutic approach to restore the anti-tumor immune response in OSCC treatment." (PMID 39940842, 2025). "With high expression of RIAD and CXCR3, MesoCAR-RIAD T cells show an enhanced trafficking and infiltration ability compared with mesoCAR T cells and exhibit enhanced tumor killing ability against mesothelin positive tumor cells." (PMID 40148310, 2025). "Overall, we delineated cell–cell interaction landscape of tumor cells and immune cells and revealed that Plac1+ tumor cells recruited CD4+ T cells through the CXCL11/CXCR3 axis and then induced Treg differentiation through PVR/TIGIT to shape the immunosuppressive TME of HNSCC." (PMID 40056047, 2025). "In addition, CXCR3 expression showed increase in TCF1+CD8+ T cells of the oHSV group, consistent with previously reported about the roles of CXCR3 in tumour immunotherapy." (PMID 39219056, 2025). "A striking feature of L-TTF2 tumors was CXCR3+CD8+-T-cell infiltration, associated with the CXCR3 ligands CXCL9/10/11/13, and tumor cell apoptosis (non-significant trend)." (PMID 40696453, 2025). "One subpopulation expressed CD44 + CXCR3 + CXCR4 + PRF1 + and GZM family genes, while the other expressed XCL1 + NCAM1 + GNLY + and KIR family genes, suggesting that these T cells possess a robust capacity to mediate tumor cell apoptosis." (PMID 40411616, 2025).